TAGAP (T cell activation RhoGTPase activating protein)
Diseases named in the same sentence as TAGAP in open-access papers (continued):
Sharing a sentence is not in itself a finding about the gene and the disease.
tumor (6 papers, 2018 to 2025). "Then, GEPIA was used to evaluate the association between TAGAP expression and immune cell signature genes of different tumor invasion types." (PMID 37744350, 2023). "In the present study, we confirmed that TAGAP can be considered as a gene associated with the tumor microenvironment and LUAD’s overall survival." (PMID 37744350, 2023). "Univariate Cox regression analysis and multivariate Cox regression analysis showed that TAGAP expression and tumor stage were risk factors for overall survival in LUAD and were independent prognostic factors." (PMID 37744350, 2023). "Further studies are warranted to fully elucidate the underlying mechanisms of TAGAP’s interaction with the tumor microenvironment and its potential clinical applications." (PMID 37744350, 2023). "TAGAP overexpression in CD4+ T cells also inhibited LUSC tumor growth and boosted immune infiltration in vivo." (PMID 39998561, 2025). "For NCI-H226 mouse xenograft tumor model, overexpression of TAGAP on CD4+ T cells inhibited tumor volume and weight; while, TAGAP silencing on CD4+ T cells accelerated tumor progression and increased weight in vivo." (PMID 39998561, 2025). "In vivo experiments in a xenograft tumor model demonstrated that TAGAP overexpression suppressed tumor growth and promoted CD4+ T cell cytotoxicity." (PMID 37744350, 2023). "TAGAP has been discovered to have crucial effects through additional pathways and systems, in addition to studies in the tumor immune microenvironment." (PMID 37744350, 2023). "In LUAD-related research, TAGAP was found to be a key gene affecting the tumor microenvironment and closely related to LUAD prognosis." (PMID 37744350, 2023). "In this study, we first analyzed the expression of TAGAP in LUAD patient tumor tissue samples using bioinformatics and collected corresponding tissue samples." (PMID 37744350, 2023). "We speculated that the regulation of TAGAP on the immune microenvironment, especially on T cells, can affect the release of cytokines, and ultimately promote the occurrence and development of tumor cells through the JAK-STAT pathway." (PMID 37744350, 2023). "Finally, we investigated whether CD4+ T cells of overexpression or silencing TAGAP could affect tumor progression in vivo." (PMID 39998561, 2025). "Therefore, we sought to investigate whether TAGAP could modulate CD4+ T cell activity, which would imply an important role of TAGAP in orchestrating anti-tumor immunity." (PMID 37744350, 2023). "In summary, our research provides initial insights into how TAGAP affects CD4+ T cell differentiation and function within the tumor microenvironment through the STAT pathway, thereby inhibiting LUAD malignancy progression." (PMID 37744350, 2023). "We extended our investigations to explore the influence of TAGAP on CD4+ T cell function, which is pivotal in orchestrating anti-tumor immune responses." (PMID 37744350, 2023). "Rasing TAGAP could rejuvenate the toxicity of CD4+ T cells and inhibit the tumor progress in vitro and in vivo, and vice versa." (PMID 39998561, 2025). "TAGAP overexpression or silencing was employed to assess its impact on cytokines production and differentiation of CD4+ T cells, downstream c-Rel expression, and tumor progression." (PMID 39998561, 2025). "More importantly, TAGAP expression was decreased in LUAD and overexpressed TAGAP could limit the tumor progress, thus increasing the toxicity and immune infiltration ability of CD4+ T cells." (PMID 39998561, 2025). "We used the Tumor Immune Dysfunction and Exclusion (TIDE) framework to confirm TAGAP’s relevance to immune cells and determine whether it has predictive value for immunotherapy." (PMID 37744350, 2023). "Moreover, TAGAP could promote the differentiation of CD4+ T cells into Th1/Th17 cells with pro-inflammatory and anti-tumor effects, while inhibiting their differentiation into Tregs with inhibitory immune responses." (PMID 39998561, 2025).
tumor (continued). "Additionally, we collected tumor tissues from 26 LUAD patients and performed immunohistochemical experiments to detect the proportion of positive cells for CD8 and CD4 surface antigen, and TAGAP in immune infiltrating cells." (PMID 37744350, 2023). "In addition, TAGAP, as a c-Rel suppressor in CD4+ T cells could promote their differentiation into Th1/Th17 cells and inhibit their differentiation into Tregs, thereby rejuvenating the anti-tumor ability of CD4+ T cells." (PMID 39998561, 2025).
cancer (3 papers, 2022 to 2023). A tumor composed of atypical neoplastic, often pleomorphic cells that invade other tissues. "TAGAP has been shown to be associated with immune cell infiltration in various cancers." (PMID 37744350, 2023). "On the other hand, the function of TAGAP in cancer is currently unknown." (PMID 37744350, 2023). "In specific, TIS is referred to as an 18‐gene signature (CCL5, GZMK, CD3D, CD3E, CD2, HLA‐DRA, IL2RG, NKG7, CIITA, CXCR6, LAG3, TAGAP, HLA‐E, CXCL13, IDO1, CXCL10, STAT1, and GZMB), which was related to the response to ICIs in various cancers." (PMID 37434432, 2023). "However, the role of TAGAP in the progression of malignant tumors remains unclear." (PMID 37744350, 2023).
infection (2 papers, 2020 to 2024). The state of being infected such as from the introduction of a foreign agent such as serum, vaccine, antigenic substance or organism. "Owing to the defective production of proinflammatory cytokines, such as IL-23a and IL-12a, in response to stimulation by Dectin ligands, TAGAP-deficient mice have decreased Th17 and Th1 cell populations, and are susceptible to Candidaalbicans infection." (PMID 32312989, 2020).
TAGAP also shares sentences with these, for which no sentence is quoted: psoriasis (3 papers); type 1 diabetes (2); candidiasis (1); coronary heart disease (1); experimental autoimmune encephalomyelitis (1); Hypertension (1); hypothyroidism (1); infectious disease (1); juvenile polyarticular arthritis (1); non-small cell lung carcinoma (1); prostate carcinoma (1); pulmonary TB (1).